MTOR (mechanistic target of rapamycin kinase)
Diseases named in the same sentence as MTOR in open-access papers (continued):
Sharing a sentence is not in itself a finding about the gene and the disease.
cancer (continued). "Metformin’s well-established anti-cancer mechanisms involve direct and indirect, AMPK-dependent and -independent inhibition of mammalian target of rapamycin (mTOR), which plays a significant role in promoting tumor proliferation as well as inhibiting apoptosis and autophagy." (PMID 35631452, 2022). "In cancer particularly, the P13K-AKT-mTOR pathway is often dysregulated and abnormally activated in human cancers in several mechanisms involving receptor tyrosine kinases (RTKs), Akt/PKB, tensin homolog (PTEN), MTOR, and other oncogene suppressor genes." (PMID 35010124, 2022). "The expression of CRNDE regulates cancer cell proliferation, migration, invasion, and apoptosis through multiple signaling pathways, such as WNT/β-catenin, PI3K/AKT, and mTOR signaling pathways." (PMID 36090045, 2022). "Since the activity of IL-37 lies mainly in the suppression of proinflammatory signaling factors such as mTOR, AKT, and PI3K, all involved in autophagy and key metabolic functions of immune and cancer cells, we further processed individual correlations with genes in these processes." (PMID 36551790, 2022). "Both the PI3K/AKT/mTOR and RAF/MEK/ERK pathways are frequently involved in cancer therapy." (PMID 36539659, 2022). "Various cancer cell lines (HT-29, SW620, MDA MB 231, MCF-7, A549, and H1299) were used as solid tumor cell models to investigate the functional impacts of miR-99b-5p overexpression in mTOR expression and subcellular distribution." (PMID 36077039, 2022). "Overall, our study suggests that co-activation of mTOR and AMPK could be a strategy to induce ER stress to combat cancer cells." (PMID 35807850, 2022). "This is particularly evident form the significant reduction in nuclear mTOR, pmTOR and AR, but slight/moderate to no reduction in cytoplasmic mTOR and AR in PCa and other cancer cells upon miR-99b-5p mimic transfection." (PMID 36077039, 2022). "Moreover, autophagy induction via upregulation of AMPK, downregulation of AKT and mTOR signaling pathways, and the induction of G2/M arrest through CDK1/cyclin B downregulation were observed in kaempferol-treated SK-HEP-1 cancer cells." (PMID 35986346, 2022). "In short, the signal transduction pathways, including mitogen-activated protein kinase (MAPK), mammalian target of rapamycin (mTOR), phosphoinositide 3-kinase (PI3K), and protein kinase B (AKT), results in cellular expansion, differentiation, hindrance of apoptosis, and cancer progression." (PMID 35774672, 2022). "In addition to NF-κB and mTOR, TBK1 can also promote cancer development and progression through other pathways." (PMID 35395857, 2022). "In addition to the mentioned small molecule inhibitors, dual PI3K/mTOR inhibitors such as GSK2126458, SF1126, LY294002, PF-04691502, LY302341, and PWT33597 have shown favorable antitumor efficacy in various malignant neoplasms." (PMID 36539659, 2022). "A classic example of a small molecule that acts as a molecular glue for the treatment of cancer is Rapamycin, which binds to mTOR immunophilin, FK-binding protein 12 (FKBP12), stabilizing the FKBP12-mTOR interaction, and subsequently, inhibiting mTOR activation." (PMID 36328247, 2022). "This implies that PI3K/Akt/mTOR inhibition could be one of the possible mechanisms by which CZE and CIN inhibit cancer growth and progression." (PMID 35774603, 2022). "miRNA targeted gene pathway interaction identified BCL7A, BCL2L1, LIN28A, KLF6, GATA6, solute carrier family genes and ZNF genes associated with erythropoiesis, cell cycle regulation, glycosphingolipid biosynthesis, cAMP, cGMP-PKG, mTOR, MAPK and PI3K-AKT signaling pathways and cancer pathways." (PMID 36295630, 2022). "High TUBA1A expression was correlated with mTOR and p38 MAPK pathways, which may control proliferation, growth, and survival of cancer cells; elevated TUBA1A expression was correlated with invasive subtypesand poor overall survival in GC patients." (PMID 36500393, 2022).
cancer (continued). "In addition, several pathways are involved in cancer cell resistance to BET inhibitors, including the activation of receptor tyrosine kinases (RTKs), JAK-STAT, phosphatidylinositol 3-kinase (PI3K), AKT/mTOR, and MAPK/ERK pathways." (PMID 35547739, 2022). "The related pathways network indicated that five copper metabolism-related cell death genes were potentially involved in other cancer-related signaling pathways, including TSC/mTOR, RTK, RAS/MAPK, PI3K/AKT, hormone ER, hormone AR, EMT, DNA damage response, cell cycle, and apoptosis pathways." (PMID 36276096, 2022). "Indeed, the antitumor activity of ropivacaine involves both the disruption of mitochondrial function and the inhibition of Akt and mTOR phosphorylation, highlighting a putative link between AKT/mTOR and mitochondrial activity in cancer." (PMID 36110954, 2022). "In addition, DET (4.14 μg/mL) decreased the phosphorylation of AKT and mTOR in SiHa cells, whereas DET upregulated the expression of the p-AKT in CNE, indicating that the effect of DET on AKT depends on the type of cancer cell." (PMID 35408483, 2022). "Notably, these pathways are intimately interconnected with each other in cancer, as ErbB signaling feeds into PI3K-Akt32 and mTOR is a major downstream module of PI3K-Akt27." (PMID 36008408, 2022). "The lack of any approved therapy to target the PI3K/AKT/mTOR pathway in pediatric and adult patients who carry germline PTEN mutations known to significantly increase their lifetime risk for cancer remains an area of unmet medical need." (PMID 36039910, 2022). "The opposite changes in the mTOR and AMPK in the GCs before anti-cancer therapy were noted." (PMID 35877414, 2022). "Other distinguished species found were mTOR (3.6 × 10−4) and its regulator, RPTOR (1.05 × 10−3), critical for controlling cancer metabolism, and structural proteins such as microtubule-associated proteins 1B, 4, and RB (1.15 × 10−3; 1.78 × 10−3; 7.3 × 10−3, respectively)." (PMID 36293503, 2022). "High dosages of mTOR inhibitors result in a significant reduction of 4E-BP1 phosphorylation and mTOR activity, all of which may be factors in ER stress, C/EBP homologous protein (CHOP), and death receptor 5 (DR5) and consequent cancer cell death." (PMID 35402264, 2022). "For cancer treatment, Fisetin inhibits the metastatic spread of different cancer cells in tumor-bearing mice by regulating a variety of pathways, such as PI3K/AKT/mTOR, Wnt/β-catenin, NF-κB, and TRAIL/TRAIL-R." (PMID 35733630, 2022). "It inhibits the mammalian target of rapamycin (mTOR) pathway and angiogenesis, and induces cycle arrest and apoptosis in cancer cells with minimal or without observed cytotoxicity on healthy cells." (PMID 36577970, 2022). "Piperlongumine inhibits cancer growth by inducing the accumulation of intracellular ROS, decreasing glutathione, damaging chromosomal DNA, and modulating key regulatory proteins, including PI3K, AKT, mTOR, NF-κB, STATs, and cyclin D1." (PMID 35954218, 2022). "We found that PBX4 in most TCGA cancers might participate in the activity of apoptosis, the cell cycle, DNA damage, hormone AR pathways, and the inhibition of TSC/mTOR, RAS/MAPK, and RTK pathways." (PMID 35740947, 2022). "mTOR pathway inhibitors are not new cancer therapeutic agents given the importance of mTOR signaling in cell growth, survival, and proliferation." (PMID 35326708, 2022). "Several mTOR inhibitors have been approved by the United States Food and Drug Administration (US FDA) for a number of cancer types; however, as single agents, these compounds have shown only limited efficacy in clinical trials, only slowing the growth of the tumors rather than being cytotoxic." (PMID 35681744, 2022).
cancer (continued). "Therefore, it is of interest to document the molecular docking analysisdata of lupeol with different cancer targets such as Caspase- 3, BCL-2, Topoisomerase, PTK, mTOR, H-Ras, PI3K, and AKT." (PMID 36518133, 2022). "Aberrant Wnt signaling which is triggered by UBE2T overexpression is a feature of advanced HCC characterized by the activation of other main oncogenic pathways such as AKT/mTOR, MAPK/ERK, and TGF‐β, which are affected differently in 2D and 3D conditions in many cancers including HCC." (PMID 34614271, 2022). "Cancers: In a series of human gastric cancer cell lines, including AGS cells, CuD (2 μM) induced apoptosis with increased reactive oxygen species (ROS) generation; these functional alterations were accompanied by reduced p-AKT and p-mTOR levels." (PMID 36355554, 2022). "In addition, CaMKII has been implicated in the activation of multiple oncogenic signaling pathways, such as the MAPK, AKT/mTOR, JAK/STAT, GSK3β/β-catenin, Notch, and NF-κB pathways, which play a critical role in cancer progression." (PMID 35267623, 2022). "In addition, quercetin-3-methyl ether stopped the growth of cancer in the esophagus by blocking the Akt/mTOR/P70S6k and MAPK pathways, which are important for the growth of cancer." (PMID 36233051, 2022). "In addition, Torin1 (ATP competitive mTOR inhibitor) and VS-5584 (PI3K/mTOR inhibitor) can significantly reduce tumor CSC levels in a variety of human cancer transplant models." (PMID 35558559, 2022). "Corroborating with these reports, we showed that the mTOR inhibitor OSI-027, an orally available anti-cancer drug currently being evaluated in Phase I clinical trial for advanced solid malignancies, exhibited significant antiviral activity against both MERS-CoV and SARS-CoV-2." (PMID 35060842, 2022). "While initial responses to PI3K/mTOR pathway inhibition are encouraging, durability tends to be limited by cytostatic responses—slowing cancer cell growth but not inducing more permanent cell death." (PMID 35484114, 2022). "However, mTOR signaling activity is enhanced in perivascular cancer cells on account of the intense anabolism, suggesting the rationale for combining PDT with mTOR inhibitors." (PMID 35413842, 2022). "Both hormones bind to receptors that are often expressed at high levels in cancer cells or in cells from which tumors originate, and that activate the oncogenic PAM (Pi3K-AKT-mTOR) pathway, leading to activation of mTOR and promoting cell proliferation and growth." (PMID 35804992, 2022). "Moreover, mTOR impairs the TCA cycle and then affects the metabolism of cancer cells by controlling mitochondrial activity and stimulating the metabolism of glutamine." (PMID 35740380, 2022). "In summary, here we report that ART controls the functional polarization of MDSCs through PI3K/AKT, mTOR, and MAPK pathways and inhibition of MDSCs by ART may provide a novel therapeutic strategy to enhance anti-PD-L1 cancer immunotherapy." (PMID 35785030, 2022). "The mTOR and AMPK expression are considered as selective markers in cancer response prediction." (PMID 35877414, 2022). "In addition, we found that they also enriched pro-cancer gene sets: KRAS signaling up, PI3K/AKT/MTOR signaling, and apical surface gene sets." (PMID 35945417, 2022).
cancer (continued). "Interestingly, searching BRSK2 against mTOR yielded several hits describing the involvement of the BRSK2 protein and TSC2 in the regulation of mTOR signaling in different contexts, including cancer cell survival and development." (PMID 36422197, 2022). "Two fundamental signal transduction pathways that may become dysregulated in a variety of cancers are RAS/MAPK (mitogen activated protein kinase) and phosphoinositide 3-kinase (PI3K)/Akt (protein kinase B)/mTOR (mammalian target of rapamycin)." (PMID 36590793, 2022). "p66Shc appears to activate mTOR, Akt, ERK, and Rac1, and regulate the activation of migration-related proteins through ROS (reactive oxygen species) in cancer cells, thus it may be involved in cancer cell development and progression." (PMID 35886904, 2022). "Genetic alterations of the PIK3CA, mTOR, PTEN, AKT1, AKT2, and AKT3 genes in human cancers." (PMID 35402264, 2022). "Therefore, detailed information on cell functions for lncRNAs targeting mTOR, S6K1, SREBP1, and HIF are shown, especially for cancer cells." (PMID 36230902, 2022). "Quantitative analyses of these assays showed that supernatants derived from the fibroblasts treated with HK1EBV cell-derived exosomes significantly enhanced DNA synthesis (lower) and activation of mTOR/p70S6K1, MEK1/2, ERK1/2, and p38 MAPK signaling, indicating enhanced cancer cell proliferation." (PMID 35986369, 2022). "Up to now, there are many mTOR inhibitors and MNKs inhibitors applied in cancer therapy, but the anticancer efficacy is not very ideal." (PMID 35737644, 2022). "In the current review, we describe the critical role of the PI3K/AKT/mTOR and RAF/MEK/ERK signaling pathways in carcinoma initiation and tumor development as potential strategies for tumor therapy, summarizing the recent doubts about targeting the pathway in monotherapy and combination therapy." (PMID 36539659, 2022). "Kinase inhibitors have shown great potential as a TNBC regimen due to their activity as antitumor and antiangiogenic therapies by targeting genes and pathways that play a role in cancer development and proliferation, like targeting EGFR, RON, MET, mTOR, BRAF, MEK, Src, and Bcr/Abl." (PMID 34944904, 2021). "As dual PI3K/mTOR inhibitors have a comparable poor toxicity profile to pan-PI3K inhibitors, with common adverse events including fatigue, nausea, vomiting and diarrhea, no dual PI3K/mTOR inhibitors have yet advanced for clinical use for any cancer type." (PMID 35582310, 2021). "Moreover, TGF-β1 can activate PI3K/AKT/mTOR signaling or promote expression of EGFR and FosB to facilitate cancer cell motility, invasion and tumor metastasis." (PMID 34203341, 2021). "Moreover, the hypoxic condition triggerred various signaling pathways such as PI3K/AKT/mTOR, ERK, and NF-κB which are involved in cancer cell survival." (PMID 34639215, 2021). "This study showed the feasibility of PDX model to explore the mechanisms of mTOR resistance acquisition and suggested that genetic alterations, including that of DNMT1, which alter the methylation status in cancer cells, are one of the potential mechanisms of developing resistance to temsirolimus." (PMID 33107222, 2021). "mTOR and ERK-1/2 signaling pathways regulate metastasis of cancer cells by modulating MMPs." (PMID 33996789, 2021). "For several cancers, the suppression of GAS5 and mTOR expression has been shown to be reciprocal." (PMID 34202777, 2021). "If the BRAF gene status did not match in the cancers and metastases, an increase in the level of mTOR mRNA, NFkBp65; VHL; ERα was observed in 32.8; 67.3; 56.0; 1.5 times." (PMID 34319022, 2021). "mTOR is a key checkpoint that negatively regulates the autophagy and inhibition of the PI3K/AKT/mTOR pathway potentially stimulates autophagy for prevention of cancer progression." (PMID 33332708, 2021). "Importantly, the knockdown of LKB1 significantly reduced the effect of CORM-2 on the proliferation of cancer cells as well as the phosphorylation of AMPK and mTOR." (PMID 34507160, 2021).
cancer (continued). "AZD8055 treatment reduced the mitochondrial content in Lkb1−/−NIC but not in control WT mice, indicating the role of mTOR activity in mitochondrial biogenesis in HER2-positive cancer." (PMID 34208071, 2021). "Inhibition of the PI3K/Akt/mTOR signaling pathway has a promising clinical efficacy since activation of autophagy by the PI3K/Akt/mTOR inhibitors can enhance treatment sensitivity and trigger cell survival once drug resistance occurs in cancer cells." (PMID 33768139, 2021). "In addition, the role of circadian clock genes in cancer-related signaling pathways, including TSC/mTOR, RTK, RAS/MAPK, PI3K/AKT, hormone ER, hormone AR, EMT, DNA damage response, cell cycle, and apoptosis pathways, were examined." (PMID 34745328, 2021). "GOLM1 is an oncogene that promotes the migration and invasion of cancer cells, and inhibits programmed cell death through stimulation of the PI3K/Akt/mTOR-signaling pathway, which may be a favorable option for the treatment of PC." (PMID 34452154, 2021). "Importantly, these are predictive biomarkers for drugs that are currently in use for treating different cancers, such as PARP, ERBB2, EGFR, PIK3CA, mTOR, and Hedgehog signaling inhibitors." (PMID 34575676, 2021). "In addition, a previous study also showed that OSBPL5 interacts with the mammalian target of rapamycin (mTOR), and the PI3K/AKT/mTOR pathway is usually active in cancer." (PMID 34829830, 2021). "Altogether, TGFβ and MMPs may act as key players in influencing mTOR and ERK-1/2 functions in cancer cells and their disparate expressions may predict different clinical outcomes." (PMID 33996789, 2021). "In addition, some reported factors, including E2F5, PTEN/AKT/mTOR signaling, DUSP11, PRPF39, and LARP4, are involved in miR-513b-5p regulated cancer progression." (PMID 34120890, 2021). "Cancer organoids derived from GBM patients were also used to test drug sensitivity to both standard-of-care chemotherapy (temozolomide) and molecular targeted agents towards mTOR, PI3K or DNA damage response." (PMID 33816288, 2021). "In cancer, it has been suggested that prolonged ERS promotes autophagy and apoptosis, and reduces resistance to chemotherapy via various mechanisms such as downregulation of the PI3K/Akt/mTOR pathway and activation of caspase-dependent apoptosis." (PMID 34208855, 2021). "The dependence of such bridges on mTOR and CDC42 makes them amenable to small molecule intervention, providing additional therapeutic strategies to modulate senescent cell behaviour in both age-related diseases and cancer." (PMID 34373767, 2021). "In addition, NORAD has interactions with cancer-related pathways, particularly STAT, TGF-β, Akt/mTOR, and PI3K/AKT pathway." (PMID 34485302, 2021). "For GSVA results of 50 hallmark pathways from the MSigDB, we found that FUCA2 was associated with many cancer-promoting and immune-related pathway, including Glycolysis, PI3K AKT MTOR signaling, TGF BETA signaling, interferon alpha and interferon gamma response in pan-cancer." (PMID 34745134, 2021). "Moreover, Diego A. Pedroza proved that PGRMC1 altered the PI3K/AKT/mTOR and EGFR signaling in TNBC cells, playing a crucial role in regulating the growth of cancer cells." (PMID 34746100, 2021). "Their activity in cellular proliferation and metabolism is highly associated with cascade activation of AKT serine/threonine kinase (AKT)/mechanistic target of rapamycin kinase (mTOR) pathways, although PI3K AKT/mTOR-independent mechanisms are also relevant to cancer development." (PMID 34683897, 2021).